SPHK1 (sphingosine kinase 1)
Diseases named in the same sentence as SPHK1 in open-access papers (continued):
Sharing a sentence is not in itself a finding about the gene and the disease.
prostate carcinoma (continued). "The SphK1b isoform was detected in 71% (5/7) prostate cancer tissues and 57% (4/7) corresponding adjacent tissues; there was no demarcation in SphK1 isoform expression to distinguish tumor stage." (PMID 36532885, 2022). "SKI-178 impaired mitochondrial functions, causing mitochondrial depolarization, reactive oxygen species production and ATP depletion.SKI-178 potently inhibited SphK activity and induced ceramide production, without affecting SphK1/2 expression in prostate cancer cells." (PMID 37604912, 2023). "They subsequently demonstrated in both PC-3 and LNCaP prostate cancer cell lines that melatonin administration significantly inhibited hypoxia-mediated phosphorylation of Akt and GSK-3β, which they determined was secondary to melatonin-induced inhibition of SPHK-1." (PMID 37191417, 2023). "Overall, our findings suggest that chrysin exerts anti-tumor activity by inhibiting SPHK-1/HIF-1α signaling and thus represents a potent chemotherapeutic agent for hypoxia, which promotes cancer progression and is related to poor prognoses in prostate cancer patients." (PMID 36139362, 2022). "However, only modulation of systemic SphK1 (not tumor SphK1), prevented S1P elevation and inhibited induced prostate cancer growth and lung metastasis." (PMID 34690821, 2021). "To confirm whether pristimerin suppresses hypoxia-induced HIF-1α accumulation via the inhibition of SPHK-1 and ROS generation in prostate cancer cells, we evaluated the effect of NAC on HIF-1α and SPHK-1 abundance in hypoxic PC-3 cells, treated with pristimerin." (PMID 27581969, 2016). "The inhibitor of the SphK1 and SphK2 isozymes, SKi (2-(p-hydroxyanilino)-4-(p-chlorophenyl) thiazole)) induced proteosomal degradation of hSphK1a and hSphK1b in androgen-sensitive prostate cancer cells, however failed to promote degradation of hSphK1b in androgen-independent prostate cancer cells." (PMID 28415564, 2017). "Since SKI-178 can block both SphK1 and SphK2, it was not surprising to show that SKI-178-induced SphK inhibition and prostate cancer cell death were significantly more potent than the SphK1 inhibitor PF-543 and the SphK2 inhibitor ABC294640." (PMID 37604912, 2023).
ovarian carcinoma (52 papers, 2011 to 2026). A malignant neoplasm originating from the surface ovarian epithelium. "Previous studies have demonstrated that SPHK1 is associated with resistance to conventional chemotherapy, and recent evidence indicates that SPHK1 enhances Olaparib resistance in ovarian cancer via the NFκB/NRF2/ferroptosis pathway." (PMID 41304867, 2025). "Using RNAseq data to analyze the cancer genome atlas (TCGA) human ovarian cancer gene expression, we explored the association of SPHK1 expression with genes involved in immunosuppression in ovarian cancer." (PMID 35289120, 2022). "Our qPCR array of all immune‐checkpoint genes in conjunction with TCGA data showed that SPHK1 or S1P directly associates with several immune checkpoints in ovarian cancer cells." (PMID 35289120, 2022). "SphK1 is often over-expressed and/or sustained-activation in ovarian cancer cells, which is associated with cancer cell survival, proliferation and apoptosis-resistance." (PMID 28938571, 2017). "We confirmed that HGSCs have elevated levels of SPHK1 mRNA, and that SPHK1 is highly expressed by ovarian cancer-associated stroma." (PMID 26716409, 2016). "Collectively, the reduced miR-124 expression and overexpressed SphK1 was probably associated in ovarian cancer tissues and cells, which indicates that SphK1 was a direct target of miR-124." (PMID 24279510, 2013). "Furthermore, SPHK1 expression is enhanced in metastatic versus primary ovarian cancer tissues, and high SPHK1 is associated with poor outcome in HGSOC patients." (PMID 40356021, 2025). "To further confirm that tumor‐associated EVs loaded with SPHK1 promote ovarian cancer progression, we performed a similar in vivo experiment by injecting SPHK1−/− ID8 cells treated with EVs isolated from parental ID8 cells or ID8 cells that ectopically expressed SPHK1." (PMID 35289120, 2022). "Exosomes derived from human ovarian surface epithelial cells transferred miR-124 to cancer-associated fibroblasts (CAFs), which suppressed the transition from normal fibroblasts to cancer-associated fibroblasts by repressing sphingosine kinase 1 (SPHK1) expression in ovarian cancer." (PMID 35024437, 2022). "In essence, this provided the possibility that the loss of miR-124 may lead to SphK1-mediated migration and invasion in ovarian cancer." (PMID 24279510, 2013). "In ovarian cancer, miR-124-3p secreted by ovarian surface epithelial cells can be transferred via exosomes to cancer-associated fibroblasts and inhibit the transition from normal fibroblasts to cancer-associated fibroblasts by targeting sphingosine kinase 1 (SPHK1)." (PMID 37248542, 2023). "In addition, whether FSH-induced activation of the Erk pathway in ovarian cancer cells causes variation in SphK1 and SphK2 expression and activity is still unclear." (PMID 32796926, 2020). "Consistent with this analysis, we observed enhanced SPHK1 gene and protein expression in metastatic compared to primary ovarian cancer tissues." (PMID 40356021, 2025). "Utilising online databases, we found enhanced expression of SPHK1 in ovarian cancer compared to normal tissues." (PMID 40356021, 2025). "Culture media from omental adipocytes significantly enhanced cell proliferation, migration and invasion of SKOV‐3 ovarian cancer cells via SPHK1." (PMID 40356021, 2025). "We observed significant positive correlations between the expression of hyaluronan synthases (HAS1‐2) and SPHK1 in ovarian cancer patient tissues (TCGA RNAseq and microarray)." (PMID 40356021, 2025). "The combination of a SPHK1 inhibitor named SKI-II or SPHK1 knockdown with curcumin has shown promising effects in enhancing growth inhibition and inducing apoptosis in ovarian cancer cells." (PMID 39875359, 2025). "SPHK1 expression was significantly increased in metastatic compared to primary ovarian cancer tissues (****p < 0.0001) and in metastatic HGSOC compared with primary HGSOC tissues (*p = 0.0301)." (PMID 40356021, 2025).
ovarian carcinoma (continued). "SPHK1 constitutes a novel promising target against ovarian cancer that warrants further investigation." (PMID 40356021, 2025). "Another study utilising RT‐PCR for snap frozen ovarian cancer tissues found significantly elevated SPHK1 gene expression in epithelial ovarian cancer compared to benign tissues." (PMID 40356021, 2025). "SPHK1 expression was significantly increased in ovarian cancer compared to OSE and FT (****p < 0.0001) and in metastatic tissues compared to FT (**p = 0.0013)." (PMID 40356021, 2025). "Selective SPHK1 inhibitor (PF‐543) significantly reduced tumour formation and ascites volume in an ovarian cancer model using ID8 mouse OSE cells." (PMID 40356021, 2025). "To confirm the relationship between SPHK1 and HA, we assessed the effects of the HA synthesis inhibitor, 4‐MU on SPHK1 protein levels in ovarian cancer cells." (PMID 40356021, 2025). "MTT and colony survival assays showed that SPHK1 knockdown ovarian cancer cells were more sensitive to olaparib." (PMID 39875359, 2025). "Utilising online databases and high‐grade serous ovarian cancer (HGSOC) patient tissue microarray cohorts, we assessed the relationship between SPHK1 expression and ovarian cancer metastasis, recurrence and patient outcome." (PMID 40356021, 2025). "PF-543, a SPHK1 inhibitor, was used to validate the role of SPHK1 in olaparib resistance of ovarian cancer." (PMID 39875359, 2025). "There is growing evidence that SPHK1 is a promising therapeutic target for multiple cancers, and this study offers a promising strategy for targeting SPHK1 in ovarian cancer patients." (PMID 40356021, 2025). "GENT2 database showed significantly increased SPHK1 expression in epithelial ovarian cancer tissue compared to OSE and FT." (PMID 40356021, 2025). "While, SPHK1 knockdown and SPHK1 inhibitor (PF-543 hydrochloride, named PF-543 in this article) enhanced the effect of olaparib on ovarian cancer cells." (PMID 39875359, 2025). "We assessed the effects of the HA synthesis inhibitor 4‐methylumbelliferone (4‐MU) on SPHK1 expression in ovarian cancer cells and HGSOC patient tissues using ex vivo tissue explant assays." (PMID 40356021, 2025). "4‐MU significantly inhibited SPHK1 expression in ovarian cancer cells (ES‐2, CaOV3 and A2780) and HGSOC patient tissues." (PMID 40356021, 2025). "A recent study showed SPHK1 inhibition by PF‐543 enhanced the sensitivity of ovarian cancer cells to Olaparib and reduced colony formation." (PMID 40356021, 2025). "Due to the pro‐tumourigenic nature of both HA and SPHK1, we further examined the relationship between SPHK1 and ovarian cancer." (PMID 40356021, 2025). "As HA is associated with tumour initiation and progression, we assessed the relationship between SPHK1 and co‐expressed genes in ovarian cancer tissues (TCGA firehose dataset)." (PMID 40356021, 2025). "Previous studies found that SPHK1 is overexpressed and promotes the proliferation, metastasis and angiogenesis of ovarian cancer." (PMID 39875359, 2025). "Epithelial SPHK1 abundance was significantly increased in metastatic tissues compared to primary ovarian carcinoma (p = 0.0033) and in metastatic HGSOC tissues compared to matched primary HGSOC tissues (p = 0.0049)." (PMID 40356021, 2025). "SPHK1 was significantly increased in ovarian cancer compared to normal tissues, elevated in metastatic and recurrent HGSOC tissues and associated with poor patient outcome." (PMID 40356021, 2025). "Our DAVID analysis of the top SPHK1 co‐expressed genes in ovarian cancer tissues (TCGA Firehose dataset, cBioportal) found positive relationships with cell adhesion, ECM organisation and positive regulation of cell migration." (PMID 40356021, 2025). "4‐MU also significantly decreased SPHK1 expression in CaOV3 (0.23‐fold change, p = 0.002) and A2780 ovarian cancer cells in monolayer culture (0.42‐fold, p = 0.00638)." (PMID 40356021, 2025).
ovarian carcinoma (continued). "Collectively, SPHK1 inhibited ferroptosis through activating NF-κB p65 transcripted NRF2 in ovarian cancer cells." (PMID 39875359, 2025). "Another interesting study demonstrated that ovarian cancer-derived EVs are packed with SPHK1/SK1, which catalyzes the phosphorylation of S1P." (PMID 39698539, 2024). "Sphingolipids are multifaceted mediators in ovarian cancer, and the sphingosine kinase 1-sphingosine 1-phosphate receptor 1 axis is altered in ovarian cancer in multiple ways and therefore represents an attractive therapeutic target." (PMID 37684587, 2023). "We next examined the amount of SPHK1 released in EVs isolated from blood samples collected from women with ovarian cancer and healthy controls." (PMID 35289120, 2022). "Taken together, our data show that high expression of SPHK1 increased both tumor burden and expression of PD‐L1 in ovarian cancer in vivo." (PMID 35289120, 2022). "It has already been shown that levels of SphK1 are significantly increased in ovarian cancer tissue." (PMID 36362323, 2022). "Overall, our data demonstrate that systemic inhibition of SPHK1 reduced both S1P‐mediated signaling and ovarian cancer growth by activating both CD4 and CD8 positive T cells." (PMID 35289120, 2022). "We found higher levels of SPHK1 in EVs secreted by ovarian cancer patients than in those secreted by healthy controls." (PMID 35289120, 2022). "There is a clear correlation between higher level of SPHK1 and poorer overall survival of the patients with lung cancer, ovarian cancer, clear cell renal cell carcinoma (ccRCC), hepatocellular carcinoma (HCC), and pancreatic cancer." (PMID 34975334, 2022). "Overall, our data uncovered a previously unrecognized oncogenic mechanism of how SPHK1‐packaged EVs upregulate S1P in the ovarian cancer microenvironment, enhancing immune suppression through T cell exhaustion." (PMID 35289120, 2022). "Using the same dataset, we also observed high levels of PD‐L1, PD‐1, FOXP3, and E2F1 in the ovarian cancer samples that expressed high levels of SPHK1 compared to samples that expressed low levels." (PMID 35289120, 2022). "SPHK1 has also been shown to play a crucial role in adipocyte-induced epithelial ovarian cancer (EOC)." (PMID 35565311, 2022). "Inhibition of SphK1 or S1PR1/3 reduced angiogenic factor secretion in epithelial ovarian cancer and clear cell renal cell carcinoma." (PMID 34069611, 2021). "It has been observed that hypoxia-induced SPHK1 expression and its downstream S1P signaling promote ovarian cancer progression, and elevated expression levels of SPHK1 or S1P are sensitive to the cytotoxic effects of metformin." (PMID 34869345, 2021). "It has been demonstrated that miR-124 exerts its anti-tumor effects via targeting SphK1 in osteosarcoma, melanoma, head, and neck squamous cell carcinoma, and ovarian cancer." (PMID 35201458, 2021). "Future clinical studies are needed to establish the clinical relevance of sphingolipid metabolism, especially focusing on targeting SPHK1 for chemotherapy-sensitizing effects in ovarian cancer patients." (PMID 33660008, 2021). "Expression analysis of SPHK1 was performed on formalin-fixed paraffin-embedded tissue from 1005 ovarian cancer patients with different histological subtypes using immunohistochemistry." (PMID 33660008, 2021). "Sphingosine-kinase-1 (SPHK1) is a key enzyme of sphingolipid metabolism which is involved in ovarian cancer pathogenesis, progression and mechanisms of drug resistance." (PMID 33660008, 2021). "In our ovarian cancer collective, high levels of SPHK1 expression correlated significantly with complete surgical tumor resection (p = 0.002) and lower FIGO stage (p = 0.04)." (PMID 33660008, 2021). "Our data identify high levels of SPHK1 expression as a potential favorable prognostic marker in ovarian cancer patients." (PMID 33660008, 2021). "Exogenous SphK1 and SphK1 overexpression was also found to induce migration, proliferation, and invasion of ovarian cancer cells in vitro." (PMID 34069611, 2021).
ovarian carcinoma (continued). "Survival analysis showed that the high levels of SPHK1, KDSR, SMPD1, GALC, SMPD2, UGCG and DEGS1 were associated with poor prognosis of OS in patients with ovarian cancer, among which DEGS1 was the most significant (P = 3E-04)." (PMID 34488809, 2021). "For instance, overexpression of SPHK1 in a xenograft model of ovarian cancer enhanced tumor growth, followed by enhancement of proliferation and stemness." (PMID 34502095, 2021). "We, therefore, investigated SPHK1 expression in cancer tissues of 1005 ovarian cancer patients with different histologic subtypes." (PMID 33660008, 2021). "In ovarian cancer, the cancer-related exosomal miR-124 targets sphingosine kinase 1 (SPHK1) and upregulates α-SMA and FAP, which differentiates NFs into CAFs and regulates CAFs migration and invasion." (PMID 32299469, 2020). "Recently, we also confirmed increased phosphe-SphK1 correlating with increased S1P in ovarian cancer cells." (PMID 32796926, 2020). "FSH stimulated the phosphorylation of both SphK1 and SphK2 and was able to regulate the survival and growth of ovarian cancer cells by activating SphK1 and SphK2 through ERK1/2." (PMID 32796926, 2020). "Collectively, our findings presented evidence that the SphK1/S1P/S1PR1/3 axis played a critical role in regulating ovarian cancer angiogenesis." (PMID 29088837, 2017). "Elevated level of SphK1 is accompanied by increased MVD in ovarian cancer tissue, which suggested the possible role of SphK in ovarian cancer angiogenesis." (PMID 29088837, 2017). "It was also reported that SphK1 promoted ovarian cancer cell proliferation and protected the cells from apoptosis through activating the survival pathways." (PMID 29088837, 2017). "Growing evidences have suggested an pivotal function of sphingosine kinase 1 (SphK1) in ovarian cancer progression." (PMID 28938571, 2017). "In our previous study, we found that the level of SphK1 was significantly increased in ovarian cancer tissues." (PMID 29088837, 2017). "Our previous study indicated that SphK1, elevated in ovarian cancer tissue, was involved in the metastasis of this deadly disease." (PMID 29088837, 2017). "Here we provided the first evidence that SphK1/S1P/S1PR1/3 pathway played key roles in ovarian cancer angiogenesis." (PMID 29088837, 2017). "Presneau and his colleagues proved that the LOH of SPHK1 assigned to chromosome region at 17q25.1-q25.2, suggesting its key role in regulating early events during the development of sensory ganglia in ovarian cancer." (PMID 28231844, 2017). "The cocultured ovarian cancer cell lines significantly induced SPHK1 mRNA in the fibroblasts in comparison to fibroblasts cultured alone (p < 0.05)." (PMID 26716409, 2016). "Using an in vitro coculture model, we found that ovarian cancer cells stimulated the transition of fibroblasts to activated myofibroblasts, and induced stromal SPHK1 expression." (PMID 26716409, 2016). "As CAFs are ultimately defined by their tumor promoting properties, we assessed the effect of SPHK1 overexpression in fibroblasts on the migration and invasion of ovarian cancer cells in vitro." (PMID 26716409, 2016). "Beach and colleagues showed a significant reduction of tumor growth and metastasis in an ovarian cancer model in Sphk1 knockout mice." (PMID 27148053, 2016). "Similar results were obtained with conditioned medium derived from ovarian cancer cell lines, suggesting that mediators secreted by ovarian cancer cells induce SPHK1 expression in ovarian fibroblasts." (PMID 26716409, 2016). "Publically-available ovarian cancer datasets confirmed elevated SPHK1 mRNA expression in ovarian cancer compared to benign ovary (Bonome dataset) or fallopian tube (the Cancer Genome Atlas [TCGA] dataset)." (PMID 26716409, 2016). "MiR-124 blocks migration and invasion of ovarian cancer cells by targeting SphK1, which would constitute a promising target for rational cancer therapy." (PMID 24279510, 2013).